GOLPH3 (golgi phosphoprotein 3)
Diseases named in the same sentence as GOLPH3 in open-access papers (continued):
Sharing a sentence is not in itself a finding about the gene and the disease.
breast carcinoma (continued). "Moreover, recombinant over-expression of mitochondrial-related proteins, such as PGC1-alpha/beta, POLRMT, MitoNEET or GOLPH3, is sufficient to promote tumor growth, by up to 3-fold, in xenografted pre-clinical models of human breast cancers." (PMID 26421711, 2015). "Furthermore, GOLPH3 was rich in mitochondrial, playing an important role in tumor metabolism, including GOLPH3-mediated autophagy resistance and mitochondrial biogenesis in breast cancer." (PMID 34497755, 2021). "This study not only suggests that the ATF-3/miR-590/GOLPH3 signaling pathway is critically involved in the proliferation of breast cancer cells, but provides a novel therapeutic target and new insight base on epigenetic regulation for future breast cancer diagnosis and clinical treatment." (PMID 29534690, 2018). "We collected data from the TCGA database of cancer and normal samples to investigated whether breast cancer patients had aberrant circulating level of GOLPH3.We found that breast cancer patients (n = 1097) showed higher level of GOLPH3 compared with normal tissue." (PMID 29534690, 2018). "Importantly, we found that high GOLPH3 expression led to a poor DFS and OS in all molecular subtypes, suggesting that GOLPH3 may be an important therapeutic target in breast cancer." (PMID 29285241, 2017). "Previously, it has been reported that GOLPH3 is amplified at the 5p13 region, and high expression of GOLPH3 has been suggested to be a predictor of poor prognosis in several types of cancer, including breast cancer, renal cell carcinoma, and esophageal squamous cell carcinoma." (PMID 26375441, 2015). "By using biochemical and fluorescence microscopy approaches, Ruggiero and coworkers explored the involvement of GOLPH3 in the metabolism of complex sialyl-glycolipids in GBM (T98G) and breast cancer (MCF7) cell lines." (PMID 40136688, 2025). "Taken together, these data indicate that GOLPH3 is an independent prognostic factor for DFS and OS in breast cancer." (PMID 29285241, 2017). "Our investigation also revealed that high GOLPH3 expression affected the DFS and OS in breast cancer patients." (PMID 29285241, 2017). "The mutational and mRNA expression status of PIK3CA, PIK3R1 and AKT1, and expression status of other genes involved in the PI3K pathway (EGFR, PDK1, PTEN, AKT2, AKT3, GOLPH3, WEE1, P70S6K) were assessed in a series of 458 breast cancer samples." (PMID 24229379, 2013). "As highlighted in the cited study, GOLPH3’s pronounced overexpression in breast cancer cells and tissues contrasts starkly with its presence in normal breast tissue." (PMID 37762375, 2023). "Furthermore, we show that GOLPH3 plays a crucial role in the formation of this GGT complex and by doing so, it influences the glycolipids profile that human glioblastoma and breast cancer cells express at the cell surface." (PMID 36142273, 2022). "GOLPH3 suppresses the forkhead box O1 (FOXO1) transcription factor via AKT signaling to regulate the expression of cell-cycle inhibitors, thereby contributing to cell proliferation and tumorigenesis in breast cancer." (PMID 33134174, 2020). "Upregulation of GOLPH3 correlates with poor response to prognosis in locally advanced rectal cancer and NSCLC.We found that GOLPH3 was significantly upregulated in breast cancer tissues compared with the normal tissues." (PMID 29534690, 2018). "Compared with adjacent noncancerous tissue and fibroadenoma samples, GOLPH3 was significantly upregulated in breast cancer tissue." (PMID 29285241, 2017). "We have found in the breast cancer cell lines MDA-MB-231 and MCF7 distinct biochemical pools of GOLPH3, which correlates with differences in some cell biological properties of this protein that could be related to the unique tumorigenic features of these cells." (PMID 30779783, 2019).
breast carcinoma (continued). "Therefore, to better understand the roles of GOLPH3 in cancer cells, we sought to compare some of its biochemical and cellular properties in the human breast cancer cell lines MCF7 and MDA-MB-231 with that of the non-tumorigenic breast human cell line MCF 10A." (PMID 27123979, 2016). "Therefore, to understand the multiple roles that the overexpression of GOLPH3 might have in oncogenesis, in this study we aimed to compare GOLPH3 in the human breast cancer cell lines MCF7 and MDA-MB-231, and in the non-tumorigenic, human breast cell line MCF 10A." (PMID 27123979, 2016).
glioma (30 papers, 2012 to 2025). A benign or malignant brain and spinal cord tumor that arises from glial cells (astrocytes, oligodendrocytes, ependymal cells). "Kindlin-2 and GOLPH3 (Golgi phosphoprotein 3) proteins are associated with glioma, and it appears that YBX1 protein is involved in the increased expression of EGFR and the activation of mTOR in this context." (PMID 38255791, 2024). "For instance, Golgi phosphoprotein 3 (GOLPH3), a protein implicated in multiple cellular functions, was reported to promote glioma progression by inhibiting Rab5-dependent EGFR endocytosis." (PMID 34831480, 2021). "In the same work, the authors showed that GOLPH3 is physically associated with both Vps35 and Wls in the U251 glioma cell line and that GOLPH3 regulates Wls at the protein, but not at the transcriptional, level." (PMID 32023813, 2020). "Expression of Golgi phosphoprotein 3 (GOLPH3), for example, has been associated with worse prognosis in human glioma patients and furthermore was shown to promote glioma progression." (PMID 29282077, 2017). "In glioma cells the molecular mechanism underlying GOLPH3 function in migration and invasion requires mTOR and one of its effectors, the transcription/translation regulatory protein Y-box binding protein-1 (YB1)." (PMID 25691054, 2015). "In a pilot study, increased expression of GOLPH3 was found in more than half of patients with glioma, and the level of GOLPH3 expression was associated with tumor severity." (PMID 23056210, 2012). "Recent studies have further emphasized that GOLPH3 is highly expressed in human gliomas and affects the proliferation, invasion, and prognosis of gliomas." (PMID 39944595, 2025). "We conclude that GOLPH3 inhibits glioma cell apoptosis and the JNK signaling pathway is either directly or indirectly regulated by GOLPH3 in glioma cells." (PMID 39944595, 2025). "In our study, using flow cytometry detection and WB experiments, we found that downregulating GOLPH3 increased the apoptosis rate of glioma u87 cells, as well as increased the expression of cleaved caspase-3, which plays a crucial role in cell apoptosis." (PMID 39944595, 2025). "Nevertheless, the role of GOLPH3 in regulating glioma cell apoptosis, a fundamental characteristic of malignant glioma, remains to be elucidated." (PMID 39944595, 2025). "Downregulation of GOLPH3 in U87 glioma cells significantly enhanced apoptosis, as evidenced by increased levels of cleaved caspase-3 and higher apoptosis rates." (PMID 39944595, 2025). "Our study indicated that downregulating of GOLPH3 in glioma U87 cells activated JNK phosphorylation and downstream signal expression, and the activated signal can be reversed by SP600125." (PMID 39944595, 2025). "The discovery of this mechanism can provide a theoretical basis for the use of JNK agonists as anti-tumor drugs in glioma patients with high expression of GOLPH3." (PMID 39944595, 2025). "For instance, insulin-like growth factor binding protein 3 (IGFBP-3), Cullin1 (Cul1), Golgi phosphoprotein 3 (GOLPH3), and aquaporin 1 (AQP1) have all been associated with glioma progression and invasiveness." (PMID 40867240, 2025). "Our previous research has shown that GOLPH3 is overexpressed in gliomas, and its downregulation hinders the proliferation of glioma cells in vitro and in vivo." (PMID 39944595, 2025). "In this study, we found that knockdown of GOLPH3 induced glioma cell apoptosis and elevated the activity of the JNK signaling pathway." (PMID 39944595, 2025). "We found that levels of JNK and c-Jun protein levels increased in the U87 cells, indicating that the JNK signaling pathway is either directly or indirectly regulated by GOLPH3 in glioma cells." (PMID 39944595, 2025). "We have confirmed that knockdown of GOLPH3 inhibits the activation of the NF-κB pathway in glioma cells and the relationship between GOLPH3 and NF-κB pathway is consistent in glioma and HCC." (PMID 39944595, 2025).
glioma (continued). "Specifically, GOLPH3 was found to promote glioma progression by inhibiting Rab5-mediated endocytosis and degradation of the epidermal growth factor receptor (EGFR)." (PMID 39944595, 2025). "We believe that the JNK signaling pathway is either directly or indirectly regulated by GOLPH3 in glioma cells." (PMID 39944595, 2025). "We used flow cytometry to detect the effect of downregulation of GOLPH3 expression on apoptosis in U87 glioma cell." (PMID 39944595, 2025). "Remarkably, combinatorial anti-tumor strategies employing GOLPH3 knockdown have already been proven effective in glioma, colon cancer, and oral squamous cell carcinoma." (PMID 38391929, 2024). "This combination of therapeutics mediated the degradation of EGFR via the inhibition of tyrosine kinase signaling and downregulation of GOLPH3 expression, resulting in overall glioma growth inhibition and enhanced survival." (PMID 39457052, 2024). "Golgi phosphoprotein 3 (GOLPH3) promotes glioma progression by inhibiting Rab 5-mediated endocytosis and degradation of EGFR." (PMID 37240137, 2023). "Angiopep-2-functionalized cationic liposomes were shown to effectively deliver siRNA against Golgi phosphoprotein 3 (GOLPH3) specifically to glioma and inhibit its growth in U87-GFP-Luci-bearing BALB/c mouse models." (PMID 35215625, 2022). "The high levels of GOLPH3 in glioma patients are related to the low survival time because of its association with tumor cells proliferation." (PMID 35456655, 2022). "Another combinatory anti-glioma system involved the dual release of Gefitinib and GOLPH3 siRNA from an Angiopep-2-modified cationic lipid-PLGA NP." (PMID 35215625, 2022). "In glioma, GOLPH3 was found to facilitates the interaction of JAK2 and STAT3, leading to activation of the STAT3 pathway." (PMID 35372504, 2022). "PKD2, on the other hand, was shown to inhibit glioma cell proliferation by upregulating Golgi phosphoprotein 3 (GOLPH3) and inducing Akt activation." (PMID 33807058, 2021). "A correlation between endocytic trafficking and GOLPH3-driven oncogenesis was suggested by a recent paper from Zhou and coauthors, which reported a role for GOLPH3 in glioma progression for inhibiting endocytosis and degradation of EGFR." (PMID 32023813, 2020). "All together, these data quite strongly support the view of GOLPH3 as a potential target for cancer therapy particularly in glioma." (PMID 32023813, 2020). "Yuan and collaborators targeted GOLPH3 through siRNA loaded on cationic liposomes, obtaining the inhibition of glioma growth in vivo, in a nude mouse model." (PMID 32023813, 2020). "This is in agreement with the effect that the reduction in the levels of GOLPH3 exerts on the proliferation of other glioma cell lines." (PMID 33238647, 2020). "In a recent work, the authors showed that GOLPH3 knockdown in U251 promotes glioma cell apoptosis and increases cellular levels of both NDRG1 and cleaved caspase 3 by ~55% and ~80%, respectively." (PMID 32023813, 2020). "A positive correlation of the protein levels of GOLPH3 and Wls in tumor samples was shown, and they were also positively correlated with tumor grade and negatively correlated with overall survival of glioma patients." (PMID 32023813, 2020). "Another piece of information about the role of GOLPH3 in glioma cell proliferation came from Zhou and collaborators." (PMID 32023813, 2020). "GOLPH3 is a oncogene that is frequently overexpressed in various malignant tumor tissues, including glioma and liver, lung, ovarian, and esophageal cancer, and is positively correlated with poor prognosis." (PMID 32454851, 2020). "The action of gefitinib was also investigated by Wang and collaborators, who found that both immortalized and primary glioma cells with higher GOLPH3 levels also display a higher sensitivity to gefitinib." (PMID 32023813, 2020). "GOLPH3 is highly expressed in glioma tissues, and its expression level is directly proportional to tumor malignancy." (PMID 33015040, 2020).
glioma (continued). "On the other hand, NDRG1 knockdown does not affect GOLPH3 expression but lowers the level of cleaved caspase 3, suggesting that GOLPH3 increases the cleavage of caspase 3 and apoptosis of glioma cells partially via downregulating NDRG1." (PMID 32023813, 2020). "We previously reported that Golgi phosphoprotein 3 (GOLPH3) promotes glioma progression by inhibiting EGFR endocytosis and degradation, leading to EGFR accumulation and PI3K‐AKT pathway over‐activation." (PMID 31094020, 2019). "Several reports have shown that GOLPH3 is overexpressed in different human tumor tissues, including gliomas, as well as in human glioma cell lines such as U87, U118 and U251 cells." (PMID 30779783, 2019). "By using the cultured primary glioma cells, we found that GOLPH3 promoted primary glioma cell growth and migration." (PMID 31094020, 2019). "In fact, in U87 and U251 cells the knocking down of GOLPH3 enhances EGFR endocytic trafficking, implying that GOLPH3 promotes the tumorigenic phenotype of these glioma cells by inhibiting the endocytosis and degradation of EGFR." (PMID 30779783, 2019). "The U251 and U87 glioma cells with GOLPH3 over‐expression exhibited higher EGFR level on the plasma membrane." (PMID 31094020, 2019). "Here, we analyzed the effect on cell migration that resulted from stable, RNAi-mediated knocking down of GOLPH3 in T98G cells of glioblastoma multiforme, a human glioma cell line with unique features." (PMID 30779783, 2019). "Taken together, our results demonstrate that GOLPH3 enhances the anti‐tumour effect of gefitinib to glioma cells." (PMID 31094020, 2019). "In this study, we found that both immortalized and cultured primary glioma cells with high GOLPH3 exhibited higher sensitivity to gefitinib treatment." (PMID 31094020, 2019). "Further researches on the clinical importance of GOLPH3 revealed that GOLPH3 expression was not only increased in oral tongue cancer and glioma, but also was indicating poor prediction and more malignant tumors." (PMID 31921678, 2019). "Both the immortalized and primary glioma cells with GOLPH3 over‐expression hold higher EGFR protein levels on the cell membrane and exhibited higher sensitivity to gefitinib." (PMID 31094020, 2019). "Firstly, we found that both the cell viability of the vector and the GOLPH3 over‐expression glioma cells decreased in a dose‐dependent manner after gefitinib treatment." (PMID 31094020, 2019). "Similar to the results found in U251 cells, the protein level/intensity of EGFR increased in GOLPH3 over‐expression GBM2 primary glioma cells and mainly located at cell membrane." (PMID 31094020, 2019). "Golgi phosphoprotein 3 (GOLPH3) is also found to be upregulated in gliomas and involved in glioma cell migration and invasion via the mammalian target of rapamycin (mTOR)-Y-box binding protein-1 (YB1) pathway." (PMID 26098895, 2015). "Our previous research indicated that GOLPH3 is upregulated in gliomas." (PMID 39944595, 2025). "However, the role played by GOLPH3 in glioma cell apoptosis and the mechanisms by which it affects cell apoptosis are still unclear." (PMID 39944595, 2025). "An in vivo glioma model was generated by implanting GOLPH3-knockdown U87 cells into nude mice." (PMID 39944595, 2025). "The increase in GOLPH3 protein levels in glioma tissues, was confirmed in our previous research." (PMID 39944595, 2025). "Interestingly, it has been shown that GOLPH3 of human glioma U251 cells interacts with the cytosolic proteins PHB1 and PHB2, which have also been observed to be associated with mitochondria." (PMID 38391929, 2024). "Moreover, in human U87 glioma cells, GOLPH3 is bound to a complex that contains RAB5 and the epidermal growth factor receptor, although a direct interaction between GOLPH3 and RAB5 remains to be established." (PMID 32790781, 2020).